SNX4 (sorting nexin 4)
Description:
Involved in the regulation of endocytosis and in several stages of intracellular trafficking. Plays a role in recycling endocytosed transferrin receptor and prevent its degradation. Involved in autophagosome assembly by regulating trafficking and recycling of phospholipid scramblase ATG9A.
Synonyms: ATG24B
Tractability: Antibody: UniProt places it where antibodies can reach, with high confidence; its Gene Ontology location is reachable by antibodies, with high confidence. PROTAC: ubiquitination databases record sites on it; its protein half-life has been measured.
Gene: Protein-coding gene on chromosome 3 (125,446,644 to 125,520,233, reverse strand). Ensembl gene ENSG00000114520.
Subcellular location: Early endosome membrane
Gene Ontology:
Molecular function: epidermal growth factor receptor binding; insulin receptor binding; leptin receptor binding; phosphatidylinositol binding; phosphatidylinositol-3-phosphate binding; protein binding; transferrin receptor binding
Biological process: endocytic recycling; positive regulation of autophagosome assembly; positive regulation of histamine secretion by mast cell; protein transport
Cellular component: cytoplasm; cytoplasmic dynein complex; early endosome; early endosome membrane; membrane; plasma membrane; protein-containing complex; SNARE complex; endosome; presynaptic endosome
Genetic constraint (gnomAD): Loss-of-function variants: 27 observed, 34.61 expected, observed/expected ratio (o/e) 0.78, 90% interval 0.57 to 1.08. The upper end of that interval is the gene's LOEUF score, 1.08, which puts it in group 4 of 6, group 1 being the genes least tolerant of losing a copy. Missense variants: 349 observed, 334.48 expected, observed/expected ratio (o/e) 1.04, 90% interval 0.95 to 1.14. Synonymous variants: 142 observed, 116.31 expected, observed/expected ratio (o/e) 1.22, 90% interval 1.06 to 1.4.
Homologues: Orthologues: chimpanzee SNX4 (100% identical), macaque SNX4 (98% identical), dog SNX4 (95% identical), mouse Snx4 (94% identical), pig SNX4 (92% identical), rat Snx4 (92% identical), rabbit SNX4 (87% identical), guinea pig SNX4 (86% identical), zebrafish snx4 (74% identical), tropical clawed frog SNX4 (30% identical). Paralogues in human: SNX2 (20% identical), SNX30 (19% identical), SNX7 (19% identical), SNX1 (18% identical), SNX18 (18% identical), SNX33 (17% identical), SNX32 (16% identical), SNX9 (16% identical), SNX6 (15% identical), SNX8 (15% identical), SNX5 (12% identical), SNX3 (11% identical), and 3 more.
Diseases named in the same sentence as SNX4 in open-access papers:
SNX4 is named in the same sentence as 9 diseases in open-access papers, as found by Europe PMC text mining. Sharing a sentence is not in itself a finding about the gene and the disease. The quoted sentences say what the papers report.
Alzheimer disease (5 papers, 2020 to 2025). A progressive, neurodegenerative disease characterized by loss of function and death of nerve cells in several areas of the brain leading to loss of cognitive function such as memory and language. "Significantly, SNX4 has already been linked with the etiology of AD, with SNX4 protein levels being decreased by 70% in the brains of severe Alzheimer’s disease (AD) cases." (PMID 40358161, 2025). "Recent studies have shown that sequenced connexin 4 (SNX4) is a synaptic protein whose altered protein levels are associated with Alzheimer’s disease." (PMID 38127902, 2023). "Altered protein levels are associated with Alzheimer’s disease, but the neuronal localization and function of SNX4 have not been addressed." (PMID 33106523, 2020).
gastric cancer (1 paper, 2022). A primary or metastatic malignant neoplasm involving the stomach. "SNX4/5/6/7/8/10/13/14/15/16/20/22/25/27/30 were overexpressed in gastric cancer, while SNX1/17/21/24/33 were higher expressed in normal tissue." (PMID 35715463, 2022).
Parkinson disease (1 paper, 2023). A progressive degenerative disorder of the central nervous system characterized by loss of dopamine producing neurons in the substantia nigra and the presence of Lewy bodies in the substantia nigra and locus coeruleus. "Green module was obtained for five Parkinson’s disease FRGs (MAP3K11, SNX4, SIRT2, NUPR1, and ACSL4)." (PMID 38127902, 2023).
prostate carcinoma (1 paper, 2015). A carcinoma that arises from epithelial cells of the prostate gland. "A prostate cancer related module was investigated (due to its significant enrichment on KEGG prostate cancer pathway), which has DEGs as PDGFRB, PDGFB, SNX2, EGFR and DECGs as (PDGFRA, PDGFRB), (SNX4, PDGFRB), (PDGFB, PDGFRA), (SNX2, PDGFRA), (PDGFRB, PIK3R2), (EGFR, PIK3R2), (EGFR, AREG)." (PMID 26070628, 2015).
viral infection (1 paper, 2021). "Increased expression was also observed for the cell-surface phagocytosis receptor, Fcgr3a, and genes linked to autophagy (Atg12, Snx4), antigen presentation pathway (RT1-CE6), Itm2a, involved in immunoglobulin production, and Oas1g, an immune response protein against viral infection." (PMID 34587117, 2021).
infection (1 paper, 2025). The state of being infected such as from the introduction of a foreign agent such as serum, vaccine, antigenic substance or organism. "It acts sequentially with SNX27, SNX4, and SNX17 along the recycling pathway in the process of the production and release of infection virions, suggesting that multiple membrane sources may contribute to the secondary envelopment of MCMV virions." (PMID 40299528, 2025).
SNX4 also shares sentences with these, for which no sentence is quoted: tumor (2 papers); cancer (1); emphysema (1).